MMP2 (matrix metallopeptidase 2)
Diseases named in the same sentence as MMP2 in open-access papers (continued):
Sharing a sentence is not in itself a finding about the gene and the disease.
tumor (continued). "Even though the Cu (II)-DOTA-CTT inhibited MMP2 and MMP9 activities with binding affinities (EC50) of 8.7 μM and 18.2 μM, respectively, which are very similar to those of the original CTT (13.2 μM and 11.0 μM, respectively), it was not successful in in vivo tumor imaging." (PMID 33918106, 2021). "Previous studies have shown that H3HR and H4HR affect tumor metastasis by regulating the EMT, whereas data from our study showed that H1HR promoted migration and invasion of HCC by inducing lamellipodia formation and up-regulating MMP-2, but not by regulating the EMT." (PMID 31740780, 2020). "Overall, the current data show multiple targets of ZR30 for its tumor suppressive effect, including membrane receptors (EGFR, NOTCH1) and their downstream AKT-signaling, pro-invasive and pro-angiogenic extracellular protease (MMP2), and oncogenic transcription factor (FOXM1)." (PMID 29290950, 2017). "However, the expression levels of MMP-2 and MMP-9 did not change significantly in primary tumor." (PMID 28819116, 2017). "MMP-2 upregulation may well represent an exaggerated host response, as LCM analysis confirmed that RNA transcripts are located primarily in the host stroma rather than epithelially derived tumour cells." (PMID 16465195, 2006). "However, we also noted that adding EVs from tumor cells, independent of the presence of CD147, increased the levels of released MMP2 and active MMP9 above that of astrocytes receiving no vesicles, suggesting that other elements in EVs may contribute to this process." (PMID 32033611, 2020). "Thus, even though no data was available on corresponding serum levels, the lack of prognostic value observed for MMP2 and MMP9 tumor expression in this retrospective cohort may argue in favor of a predictive and specific impact of these markers for bevacizumab benefit." (PMID 26921265, 2016). "Although bexarotene did not significantly change MMP2 secretion in A549 cells and MMP9 in MDA-MB-231 cells, the decreased amount of other matrix metalloproteinases and elevated level of TIMPs may result in an increased ratio of TIMP to MMP leading to a decrease in tumour cell invasion." (PMID 16495926, 2006).
cancer (2,580 papers, 1998 to 2026). A tumor composed of atypical neoplastic, often pleomorphic cells that invade other tissues. "CD147 has been implicated in cancer cell migration and invasion through the induction of matrix metalloproteinases (MMPs), including MMP-2 and MMP-9." (PMID 41123660, 2025). "HSP70 plays a role in cancer stemness by increasing the expression of cancer stemness-associated proteins (such as vimentin, N-cadherin, MMP-2, MMP-9, Snail, Slug, Twist, and others)." (PMID 41369386, 2025). "Given that Smad2/3 activation is associated with the expression of MMP2, a key mediator of cancer metastasis, we examined MMP2 levels and found that AML-exos upregulated MMP2 expression in Thp-1 cells, which was reversed by ITD1." (PMID 41020812, 2025). "In pancreatic cancer, MMP-2, expressed by activated pancreatic stellate cells, is associated with cancer progression in contrast to MMP-9, which seems to coordinate immune cell infiltration." (PMID 40332096, 2025). "HDAC6 is involved in increasing cancer cell proliferation and the stress response, whereas MMP2 has been linked to cancer cell invasion and a poor prognosis." (PMID 40429793, 2025). "Previous research showed the upregulation of MMP-2 expression associated with cancer invasion in various tumors." (PMID 40894070, 2025). "FAK/Src pathway induces Akt activation in cancer cells, leading to high secretion of MMP-2 and MMP-9, which eventually causes proliferation, migration, invasion, and metastasis." (PMID 40040878, 2025). "Dysregulation of MMP-2 has been linked to a variety of pathological conditions, including cardiovascular diseases, diabetic complications, kidney diseases, and cancer." (PMID 39769454, 2024). "Replacement of the C allele with T in the −1306 location has been shown to decrease the promoter activity of the MMP‐2 gene alongside reducing cancer susceptibility." (PMID 39610026, 2024). "Increased TIMP-2 levels positively correlate with MMP-2 activation and poor prognoses in cancer patients, with a clear association between TIMP-2 levels and cancer cell migration." (PMID 39684484, 2024). "Multiple studies indicate that EGCG possesses anti-migratory and anti-cancer properties associated with the downregulation of MMP-2 and MMP-9." (PMID 39335164, 2024). "The overactivation of MMP2 is associated with cancer cell invasion and metastasis by degrading the extracellular matrix, facilitating cancer cell penetration through tissue boundaries and entry into the vascular system." (PMID 39518808, 2024). "Matrix metalloproteinase 2 (MMP2) is closely associated with metastasis and malignant tumor dissemination." (PMID 39444611, 2024). "Matrix metalloproteinase-2 (MMP2) has been implicated in cancer progression due to its role in extracellular matrix degradation, yet comprehensive studies linking MMP2 expression to CRC progression and its molecular mechanisms remain needed." (PMID 38978899, 2024). "MMP-2 activity was assessed via zymography, and susceptibility to malignant arrhythmias was tested ex vivo." (PMID 39766216, 2024). "In a nutshell, MMP2 gene is an important biomarker gene in cancer that can serve as a diagnostic, prognostic, and therapeutic target." (PMID 38560573, 2024). "Regarding cancer proliferation and invasion-associated markers, Ki67, MMP2, and MMP9 protein levels were significantly decreased following PLK1 knockdown relative to the si-NC group." (PMID 39524172, 2024). "The detection of MMP2 in these samples can potentially serve as a diagnostic and prognostic tool in cancer." (PMID 38560573, 2024). "MMP-2 is associated with angiogenesis, tissue remodeling, and tumor invasion, making it an important enzyme in cancer progression." (PMID 38544822, 2024). "Matrix metalloproteinase (MMP)-2 and -9, which degrade type IV collagen, are linked to cancer invasion and metastasis." (PMID 39063556, 2024).
cancer (continued). "Several studies have shown that the expression of MMP2/9 is regulated by the STAT3 signaling pathway in a variety of solid tumors, suggesting that increased activation of STAT is the cause of upregulation of MMP2/9 expression in cancer cells." (PMID 38835342, 2024). "All of these results confirm EGCG’s ability to suppress cancer formation, mainly by modulating MMP-2, MMP-9, and associated pathways." (PMID 39335164, 2024). "MMP-2 has been shown to be activated in a cancer-associated fibroblast-conditioned medium, leading to increased invasion of keratinocytes in a TGF-β-dependent manner." (PMID 39769454, 2024). "Transwell invasion assay and the expression alterations of cancer metastasis-associated proteins (MMP2/9, TIMP1/2) showed an accelerative effect of RP11-79H23.3 siRNA on the metastasis capability of NSCLC cells." (PMID 35972581, 2023). "Matrix metalloproteinase (MMP)-2 and -9 are gelatinases which are capable of degrading type IV collagen and have been linked to cancer invasion and metastatic development." (PMID 37445754, 2023). "Extracellular matrix remodeling was the main cause responsible for stimulating cancer spread and metastasis, particularly matrix metalloproteinases (MMPs), involving MMP-2, -9, -11, and -14, that destroy the matrix proteins." (PMID 37062547, 2023). "Compared to static culture, perfusion flow induced higher cell proliferation rates (20% vs. 5%), enhanced secretion of active MMP-2, and upregulation of the Rho pathway, associated with cancer cell dissemination." (PMID 37296184, 2023). "Concomitantly, MMP2 overexpression is associated with a higher risk of cancer metastasis, and MMP9 overexpression correlates to lymph node metastasis." (PMID 37239013, 2023). "Transwell invasion assay and the expression changes of cancer metastasis-associated proteins (MMP2/9, TIMP1/2) suggested an enforced impact on cell invasion ability in miR-29c mimics group whereas an impaired effect in Anti-miR-29c group." (PMID 35972581, 2023). "The role of intracellular MMP‐2 is increasingly being implicated not only in cancer cell invasion, but also in cell migration." (PMID 38064181, 2023). "Cancer associated fibroblast cells were identified through the classic Maker gene (Mmp2, Apod, Dcn, and Col1a1) in all cells." (PMID 36382024, 2022). "As the combination of DADS and SORA inhibited the migration and invasion of HepG2 cells, we measured the mRNA levels of Matrix metalloproteinase 2 (MMP2), which has been associated with cell migration in cancer." (PMID 36559076, 2022). "Cancer cell invasion and metastasis is assisted by activities of MMP-2 and MMP-9 which are associated with promoting cell-cell and cell-matrix interactions during the EMT." (PMID 36147907, 2022). "It was therefore revealed that the decreases in cancer cell migration and invasion caused by Stellettin B are associated with downregulation of the activities and protein expressions of MMP-2 and MMP-9." (PMID 36483979, 2022). "Matrix metalloproteinases-2 (MMP2) is implicated in the invasion, development, and metastasis of the majority of human cancers due to their propensity to degrade the surrounding connective extracellular matrix (ECM)." (PMID 36104946, 2022). "Here, conditioned media from WIN 55,212-2-treated cancer-associated fibroblasts were shown to impair the invasive properties of prostate cancer cells due to a cannabinoid-mediated reduction in MMP-2 release." (PMID 35277658, 2022). "For metalloproteinase 2 (MMP2), an epigenetic control by promoter hypomethylation was suggested to be associated with invasive cancer behaviour." (PMID 35571032, 2022). "Increased expression of MMPs has been associated with a poor prognosis of aggressive cancer, especially MMP-2 and MMP-9." (PMID 36605288, 2022). "MMP-2 is correlated with the development of different types of cancers and associated with poor prognosis." (PMID 36544756, 2022).
cancer (continued). "It has been discovered that MMP-2 overexpression across almost all types of cancer is linked to a feature of cancer aggressiveness and malignancy." (PMID 35586209, 2022). "In particular, MMP-2 and -9 secretion is increased in several types of human cancer, and their increased expression is associated with poor prognosis." (PMID 33567682, 2021). "The miRNA-associated regulation of MMP-2 expression is a critical mechanism in the development, progression, migration and metastasis of cancer cells." (PMID 34283074, 2021). "Cancer-associated fibroblasts (CAFs) also stimulate omental metastasis of cancer cell through TGF-β-activated of MMP-2." (PMID 34277625, 2021). "Further, we observed the expression of the cancer-related markers, MMP2, β-catenin, and integrin β1, which are associated with matrix stiffness and correlated with cancer cell invasion and metastasis." (PMID 33816446, 2021). "MMP9+/MMP2+/EMMPRIN+ subpopulation of CD9-positive blood plasma exosomes reduced the cancer risk in CPPs." (PMID 33773551, 2021). "MMP2/9 have also been implicated in cancer development and progression through their functions in cell apoptosis, proliferation, and angiogenesis." (PMID 33568081, 2021). "By suppressing the activity of MMP-2, curcumin administration has been associated with inhibiting cancer progression." (PMID 34456716, 2021). "In both OC and CC, MMP-2 and -9 are implicated in cancer cell invasion and metastasis and are associated with poor survival." (PMID 35145899, 2021). "As a matrix metalloproteinase, the abnormal expression of MMP2 is associated with multiple biological processes, including tissue remodeling and cancer progression." (PMID 34976953, 2021). "In particular, the elevated MMP-2 activity during carcinogenesis is associated with angiogenesis and cancer cell migration." (PMID 33670389, 2021). "Amongst involved proteases, MMP-9 and MMP-2 are profoundly implicated in cancer invasion and metastasis as they are the most essential for the degradation of base membranes." (PMID 34068885, 2021). "MMP2 is a zinc-dependent endopeptidase that causes the breakdown of a subset of extracellular matrix components during cancer metastasis." (PMID 34831316, 2021). "For instance, MMP-9 and MMP-2 upregulation is reportedly associated with cancer cell migration in various cancers." (PMID 32397656, 2020). "Analysis showed that only MMP-2 overexpression by cancer cells in peritoneal implants was associated with a significant risk of death by progression of the disease." (PMID 32751899, 2020). "Col 1 increases migration of three RCC cell lines and stimulate MMP-2 and 9 activity, two metalloproteinases implicated in cancer cell invasion and metastasis formation." (PMID 32411604, 2020). "High expression of MMP-2 in cancer cells was associated with decreased survival of colon cancer patients." (PMID 32751899, 2020). "In recent years, the importance of cancer-associated proteases such as matrix metalloproteinases MMP-2 and MMP-9 in invasion and metastasis has been reported for a variety of solid malignant tumors." (PMID 33348592, 2020). "Here, we show that in vitro collective cancer cell migration depends on FAK and MMP-2 and on the presence of cancer-associated fibroblasts (CAFs)." (PMID 33321813, 2020). "Our study found multiple genes in the cancer pathway that are associates with the progression or suppression of cancer such as laminin, Tgfβ3, Hhip, Arnt2 and Mmp2." (PMID 32330152, 2020). "Gain-of-function mutations in RET lead to the development of specific human cancers and have been associated with the regulation of MMPs, including MMP2 and MMP9, which are thought to drive metastasis." (PMID 33020210, 2020). "Their dysregulation is associated with numerous pathological conditions and cancers, with the MMP2 isoform intrinsically involved in cancer invasion and metastasis." (PMID 32987782, 2020).
cancer (continued). "The elevated levels of enzymatic activity of CatB and MMP2 are linked to a variety of medical conditions, such as cancer metastasis." (PMID 32349205, 2020). "MMP2/9 is significantly dysregulated in human cancers and is associated with poor prognosis and detrimental immune features." (PMID 32988398, 2020). "An involvement of HSP90α in TRPM7-dependent HSP90α/uPA/MMP2 signaling was associated with extracellular proteinase activity, expression of cancer stemness markers, multicell spheroid-forming ability, and high metastatic potential of lung CSC-like cells." (PMID 32268506, 2020). "Mechanistically, luteolin-7-O-glucoside caused a reduction in cancer metastasis by reducing p38 phosphorylation and downregulating matrix metalloproteinase (MMP)-2 expression." (PMID 32224968, 2020). "TIMP-2 mutations on chromosome 17q25 can affect its binding to MMP-2, resulting in cancer development." (PMID 33027062, 2020). "We, therefore, examined the effects of the anti-cancer drug on the expression of MMP2 and VEGF, a factor associated with cancer metastasis, in LLC-inoculated C57BL/6N mouse stocks." (PMID 32257905, 2019). "As a consequence, we found cancer stem cell-associated proteins, such as mmp2, mmp9, mmp13, mmp14, paxillin, Ras, src and c-myc, as well as genes expressed in the immune system, such as C5, C9, and HMGB1." (PMID 31832023, 2019). "Taken together, we identified a potential regulatory mechanism of p16INK4a/MMP-2 expression in cancer by loss of function of p21WAF1/Cip1 through the interaction with hYSK1 in hypoxia." (PMID 30646538, 2019). "For example, EV-associated heat shock protein-90 released by invasive cancer cells induce the expression of MMP-2 which activates plasmin, a second protease that promotes cancer cell invasion." (PMID 30322133, 2018). "Our strategy can also significantly inhibit cancer migration and invasion, associated with altered expression of MMP-2/− 9, E-cadherin, vimentin and snail." (PMID 29587668, 2018). "With regard to the mechanism by which miR-137 regulates the MMP-2 and, subsequently, causes the suppression of cancer invasion by ISO treatment, we discover that GSK3β plays an essential role in mediating these observed effects." (PMID 30195772, 2018). "HSP90α is the secreted isoform and is associated with MMP2, implicating extracellular Hsp90 in cancer metastasis." (PMID 30477473, 2018). "Hypoxia in cancer cells caused up-regulation of MMP-2/9 in both MDA-MB-231 and MDA-MB-468 cancer cells." (PMID 29695771, 2018). "In 5-Aza treated cells, the expression of cancer associated invasive markers was tested (E-Cadherin, N-Cadherin, Vimentin, Twist, MMP-2, and MMP-9)." (PMID 29695771, 2018). "Another hallmark of cancer is the evasion of immune-cell-mediated cytotoxicity, and MMP-2, via the regulation of chemokine activity, can also play a contributory role in this aspect of the disease." (PMID 29874869, 2018). "Elevated MMP-2/-9 levels are associated with pro-inflammatory states that can induce or amplify diseases, such as cardiac disease, arthritis and cancer, suggesting a role for inhibitors in disease prevention or treatment." (PMID 30248101, 2018). "Several lines of evidence also revealed that inhibition of ERK1/2 is associated with MMP-2 down-regulation to suppress cancer progression." (PMID 30359388, 2018). "MMP-2 is a secreted protein implicated in the destruction of broad range of ECM substrates in various cancers." (PMID 28915621, 2017). "MT1-MMP, a membrane-bound matrix metalloproteinase (MMP) localizing to the leading edge of invasive cells, degrades ECM components and activates latent MMP-2, therefore has been strongly implicated in metastasis of multiple types of cancers." (PMID 28388589, 2017). "Recently, a meta-analysis that investigated the association of the MMP2 −1306C/T polymorphism with cancer risk reported that the SNP was significantly correlated with reduced risk of cancer, which is consistent with our results." (PMID 29069837, 2017).